TNNI3K (TNNI3 interacting kinase)
Description:
May play a role in cardiac physiology.
Synonyms: CARK; CCDD
Tractability: Small molecule: a structure with a bound ligand is known; a high-quality ligand is known; it belongs to a druggable protein family. PROTAC: ubiquitination databases record sites on it; a small molecule that binds it is known.
Target class: Protein Kinase; Enzyme; TKL protein kinase HH498 subfamily; TKL protein kinase group; Kinase; TKL protein kinase MLK family
Gene: Protein-coding gene on chromosome 1 (74,235,285 to 74,544,432, forward strand). Ensembl gene ENSG00000116783.
Subcellular location: Nucleus; Cytoplasm
Gene Ontology:
Molecular function: protein binding; protein kinase activity; protein serine kinase activity; ATP binding; protein serine/threonine kinase activity
Biological process: bundle of His cell to Purkinje myocyte communication; peptidyl-serine autophosphorylation; protein phosphorylation; regulation of cardiac conduction; regulation of cardiac muscle contraction; regulation of heart rate
Cellular component: cytoplasm; nucleus
Genetic constraint (gnomAD): Loss-of-function variants: 128 observed, 105.61 expected, observed/expected ratio (o/e) 1.21, 90% interval 1.05 to 1.4. The upper end of that interval is the gene's LOEUF score, 1.4, which puts it in group 5 of 6, group 1 being the genes least tolerant of losing a copy. Missense variants: 1,085 observed, 1,010.9 expected, observed/expected ratio (o/e) 1.07, 90% interval 1.02 to 1.13. Synonymous variants: 340 observed, 356.49 expected, observed/expected ratio (o/e) 0.95, 90% interval 0.87 to 1.04.
Gene-disease validity (ClinGen):
ClinGen rates the evidence that TNNI3K causes each of these diseases.
dilated cardiomyopathy (autosomal dominant): Moderate. Cardiomyopathy which is characterized by dilation and contractile dysfunction of the left and right ventricles.
Homologues: Orthologues: chimpanzee TNNI3K (99% identical), macaque FPGT (97% identical), pig TNNI3K (96% identical), rabbit TNNI3K (96% identical), dog TNNI3K (95% identical), rat Tnni3k (91% identical), mouse Tnni3k (91% identical), tropical clawed frog tnni3k (89% identical), zebrafish tnni3k (85% identical), Caenorhabditis elegans sel-15 (45% identical). Paralogues in human: LRRK2 (18% identical), LIMK1 (17% identical), BRAF (17% identical), MAP3K10 (17% identical), MAP3K21 (17% identical), KSR2 (16% identical), MAP3K9 (16% identical), LIMK2 (16% identical), RAF1 (16% identical), MAP3K13 (15% identical), KSR1 (15% identical), MAP3K11 (15% identical), and 11 more.
Diseases named in the same sentence as TNNI3K in open-access papers:
TNNI3K is named in the same sentence as 40 diseases in open-access papers, as found by Europe PMC text mining. Sharing a sentence is not in itself a finding about the gene and the disease. The quoted sentences say what the papers report.
cardiomyopathy (15 papers, 2009 to 2025). A disease of the heart muscle or myocardium proper. "Collectively, we generated a splice site mutation in the zebrafish tnni3k gene that led to cardiac dysfunction and conduction disorder, recapitulating several key features of human TNNI3K mutation-caused cardiomyopathy and CCD." (PMID 39926332, 2025). "Here, we employed the CRISPR/Cas9 gene-editing technique to generate a splicing mutation in the 4th exon of zebrafish tnni3k ortholog gene that mimics a TNNI3K splicing variant identified from a patient family with cardiomyopathy and CCD." (PMID 39926332, 2025). "This case report highlights the complex interplay between genetic variants in the DMD and TNNI3K genes, resulting in extremely early onset of cardiomyopathy in a patient with DMD." (PMID 40134720, 2025). "More studies are needed to validate these findings in large mammalian animal models and to develop NFATC1 nuclear translocation-targeted therapeutic strategies for TNNI3K gene mutation-based cardiomyopathy and CCD." (PMID 39926332, 2025). "An affected sibling was homozygous for the missense variant, and whilst TNNI3K variants are typically associated with a dominant form of cardiomyopathy, the parents were unaffected heterozygous carriers." (PMID 36672924, 2023). "Mutations in TNNI3K were identified in patients with cardiac conduction diseases, arrhythmias, and cardiomyopathy." (PMID 37628941, 2023). "In summary, 3 years of diagnostic testing of TNNI3K in arrhythmia and cardiomyopathy patients yielded 2 missense variants (TNNI3K-p.Ile512Thr [1 family] and TNNI3K-p.His592Tyr [7 families]) in TNNI3K with cosegregation with DCM, SVT, and CCD." (PMID 37199186, 2023). "The Tnni3k-correlated genes were mainly found to be associated with insulin resistance and cardiomyopathy signaling pathways." (PMID 37628941, 2023). "Here, we show the yield of 3 years of diagnostic testing of TNNI3K in arrhythmia and cardiomyopathy patients." (PMID 37199186, 2023). "The rs49812611 has been experimentally linked to aberrant TNNI3K protein expression in the D2 strain, which is known to display cardiomyopathy traits including cardiac hypertrophy and fibrosis." (PMID 37628941, 2023). "The TNNI3K has been linked to a broad spectrum of cardiac phenotypes in mice, such as accelerated cardiomyopathy and cardiac conduction." (PMID 35274013, 2022). "Human genetic variants in TNNI3K are associated with supraventricular arrhythmias, conduction disease, and cardiomyopathy." (PMID 34203974, 2021). "Excessive expression of TNNI3K is strongly implicated in the progression of cardiomyopathies." (PMID 36983924, 2023). "We found that this variant would lead to a decrease in the level of TNNI3K mRNA and protein, as well as a decrease in the expression of the RYR2 gene, which further proves that TNNI3K plays an important role in cardiomyopathy and expands the spectrum of the TNNI3K variants." (PMID 35274013, 2022). "Variants in TNNI3K are associated with supraventricular arrhythmias, cardiomyopathy, SCD, and CCD." (PMID 34203974, 2021). "This tnni3k heterozygous mutant (tnni3ke4/+) recapitulated several key features of cardiomyopathy and CCD, thus representing a novel model of human TNNI3K mutation-based cardiac diseases." (PMID 39926332, 2025). "In conclusion, we generated a unique zebrafish animal model of TNNI3K splicing mutation-based cardiomyopathy and CCD and identified the focal adhesion pathway and Mypt1/Mlc2/Yap1/Nfatc1 axis as the downstream phosphorylation targets of the Tnni3k protein." (PMID 39926332, 2025). "We found that pharmacological inhibition of the translocation of Nfatc1 into the nucleus partially alleviated the cardiomyopathy phenotypes in the heterozygous tnni3k splicing mutant zebrafish model." (PMID 39926332, 2025). "Seven variants (41%) were detected in genes associated with cardiomyopathies including CSRP3, LAMA4, MYH6, MYBPC3, TNNI3, TNNI3K, and TNNT2." (PMID 39272661, 2024).
cardiomyopathy (continued). "In the studied period, 2467 probands underwent genetic examination of the arrhythmia or cardiomyopathy panel including TNNI3K, or both." (PMID 37199186, 2023). "We also provide evidence for novel (recessive) modes of inheritance of a well-established gene TNNI3K and expand our knowledge of the clinical heterogeneity of cardiomyopathies." (PMID 36672924, 2023). "To investigate the effect of hyperglycemia on myocardial damage markers, we compared the expression of TNNI3K, a kinase of the MAPK signaling cascade implicated in cardiomyopathies, between the NT and HG groups by immunofluorescence." (PMID 36983924, 2023). "Together these results highlight an autosomal recessive form of TNNI3K-cardiomyopathy that should be considered particularly in consanguineous populations." (PMID 36672924, 2023). "Subsequently, another study reported that, in addition to cardiomyopathy, transgenic mice overexpressing TNNI3K have high plasma levels of troponin I and a greater number of heart attacks." (PMID 36983924, 2023). "Genetic variants L513P, G526D, T539A, and E768K all reduce the kinase activity of TNNI3K, identified in patients with cardiomyopathies and arrhythmias." (PMID 37628941, 2023). "Our gene-based meta-analyses identified a burden of rare coding variants associated with QT, JT, and QRS, in genes typically linked with inherited channelopathies (KCNQ1, KCNH2) and cardiomyopathies (MYH7, TNNI3K)." (PMID 36050321, 2022). "We here provide an overview of the role of TNNI3K in cardiomyopathy and arrhythmia covering both a clinical perspective and basic science advancements." (PMID 34203974, 2021). "Studies have shown that TNNI3K plays a vital role in important parts of cardiac biology and heart diseases, including viral myocarditis, cardiomyopathy, and cardiac conduction, indicating that TNNI3K is a promising target for the treatment of heart diseases." (PMID 34136567, 2021). "Tnni3k was recently identified as a genetic modifier of disease progression in the Csqtg mouse model of cardiomyopathy." (PMID 23236294, 2012). "Here we report the identification of a novel heart disease modifier gene, Tnni3k, that accelerates disease progression in two distinct mouse models of cardiomyopathy." (PMID 19763165, 2009). "To mimic the cardiomyopathy and CCD caused by this human TNNI3K variant, we designed a single guide RNA targeting the splicing donor site of the 4th exon in the zebrafish tnni3k gene and generated a splicing mutant in the predicted splice donor site via CRISPR/Cas9 technology." (PMID 39926332, 2025). "Additionally, a previous in vivo study reported cardiomyopathy and heart failure in transgenic mice overexpressing TNNI3K." (PMID 36983924, 2023). "In fact, historical studies of cardiomyopathy in B6 and D2 backcrosses have identified a QTL that was later discovered to be caused by an intronic variant in the tropin-interacting kinase gene Tnni3k, which also conferred susceptibility to viral-induced myocarditis." (PMID 37405387, 2023). "The TNNI3K expression greatly accelerates the cardiac dysfunction in cardiomyopathy mouse models." (PMID 35274013, 2022). "In addition, inhibition of TNNI3K or PDE5A was shown to be cardioprotective against several cardiomyopathies." (PMID 35172813, 2022). "We next investigated whether TNNI3K expression would exhibit a disease accelerating effect in a model of cardiomyopathy that was unrelated to Calsequestrin over-expression." (PMID 19763165, 2009). "Although these experiments determined the molecular mechanism underlying the observed differences in Tnni3k transcript levels, they did not address the in vivo role of Tnni3k in the progression of cardiomyopathy." (PMID 19763165, 2009). "Importantly, recombinant inbred (RI) mice derived from crosses of B6 and D2 strains, the so-called BXD family of murine genetic reference population (GRP) segregated those cardiomyopathy traits, suggesting a potential relation between cardiomyopathy traits and Tnni3k." (PMID 37628941, 2023).
cardiomyopathy (continued). "In vivo transgenic and congenic mouse lines confirm that TNNI3K levels are a significant determinant of the rate of disease progression and outcome, since expression of this protein accelerates disease progression in two independent and unrelated models of cardiomyopathy." (PMID 19763165, 2009). "In this study, we reported a TNNI3K variant in ARVC for the first time, and the results not only contribute to the diagnosis of ARVC, but also provide a reference for genetic counseling and promote the understanding of the genetic mechanism of cardiomyopathy." (PMID 35274013, 2022). "Consequently, TNNI3K expression alone did not result in overt cardiomyopathy or decreased survival due to heart failure." (PMID 19763165, 2009).
dilated cardiomyopathy (10 papers, 2019 to 2025). "The pathogenic variants of TNNI3K have been associated with a spectrum of cardiac conditions, including dilated cardiomyopathy, atrial fibrillation, and conduction system diseases." (PMID 40134720, 2025). "Genetic variants in TNNI3K (troponin-I interacting kinase) have previously been associated with dilated cardiomyopathy (DCM), cardiac conduction disease, and supraventricular tachycardias." (PMID 37199186, 2023). "Then, a splicing variant, TNNI3K-c.333 + 2T>C, leading to haploinsufficiency was reported in patients with dilated cardiomyopathy and/or CCD and a history of syncope and sudden death." (PMID 33664309, 2021). "Possibly, families with conduction system disease and dilated cardiomyopathy share other genetic alterations or environmental conditions that combine with the heterozygous TNNI3K variants to cause disease." (PMID 31589606, 2019). "In several human pedigrees, mutations in the TNNI3K gene have been associated with conduction system disease (of various manifestations) and dilated cardiomyopathy." (PMID 31589606, 2019). "A preponderance of evidence suggested that TNNI3K is associated with a broad spectrum of cardiac phenotypes including CCD, dilated cardiomyopathy, and supraventricular tachycardia." (PMID 32529721, 2020). "The TNNI3K gene encodes TNNI3-interacting kinase and is typically associated with an autosomal dominant cardiac conduction disorder with or without dilated cardiomyopathy (OMIM: 616117)." (PMID 36672924, 2023). "Our study is consistent with previous studies which demonstrated that TNNI3K mutations were related to CCD with or without dilated cardiomyopathy." (PMID 32529721, 2020). "TNNI3K-G526D was identified in a three-generation family of patients with CCD, atrial tachyarrhythmia and dilated cardiomyopathy vulnerability." (PMID 33664309, 2021). "Although TNNI3K is involved in dilated cardiomyopathy (DCM), its involvement in ARVC has not been reported." (PMID 35274013, 2022).
cardiac conduction disease (9 papers, 2020 to 2025). "Familial atrial tachyarrhythmia subfascicular heart conduction disease is an autosomal dominant genetic disease caused by TNNI3 interacting kinase (TNNI3K) mutation, with a prevalence of <1:1,000,000." (PMID 39596569, 2024). "Recent studies demonstrated that non-sense TNNI3K mutation, associated with cardiac conduction disease (CCD) and harboring the mutation c.1441C > T, has implicated a loss-of-function pathogenic mechanism with an autosomal-dominant inheritance pattern." (PMID 35274013, 2022). "Moreover, mutations in TNNI3K have also previously been linked to the conduction heart disease spectrum (MIM 616117)." (PMID 34440456, 2021). "The expression of mutant TNNI3K decreased, which is consistent with the results of known pathogenic mutations in DCM and cardiac conduction disease (CCD)." (PMID 35274013, 2022). "Furthermore, we demonstrate genetic segregation for 2 rare variants, TNNI3K-p.Ile512Thr and TNNI3K-p.His592Tyr, with phenotypes consisting of DCM, cardiac conduction disease, and supraventricular tachycardia, together with increased autophosphorylation." (PMID 37199186, 2023). "Previous investigations have demonstrated that TNNI3K has a key role in both sarcomere organization and heart development; hence, decreased TNNI3K mRNA levels might lead to DCM and cardiac conduction disease." (PMID 37183561, 2023).
Obesity (9 papers, 2015 to 2025). Accumulation of substantial excess body fat. "The association of TNNI3K with obesity has been replicated in both in EA children and HA women." (PMID 26537541, 2015). "TNNI3K has been associated with increased intake of fats and sugary foods in overweight or obese adults with Type 2 diabetes, and has been nominally associated (p < 0.05) with emotional and uncontrolled eating, suggesting a potential mechanism for influencing obesity." (PMID 26537541, 2015). "In studies conducted in adults, SNPs in the genes FTO, MC4R, TMEM18, TNNI3K, SEC16B, GNPDA2, and POMC are strongly associated with obesity risk." (PMID 40722558, 2025). "Several as of yet not replicated studies on carcinogenesis, viral infection, and obesity further expand the spectrum of potential roles of TNNI3K." (PMID 38701081, 2024). "Both smoking and obesity increase systemic oxidative stress and risk of cardiovascular disease (CVD), and the influence of TNNI3K on cardiac function suggests a possible biological pathway for this interaction." (PMID 26537541, 2015). "Although the precise mechanisms remain unclear, these findings highlight TNNI3K as a gene of interest in obesity research." (PMID 41082226, 2025). "Multiple studies have reported the relevance of SNPs near or in the TNNI3K loci (rs1514175, rs1514176, rs12142020, rs274609), creating a variant in the TNNI3K or FPGT-TNNI3K transcript, which are positively associated with body mass index, eating behavior, and (child-)obesity." (PMID 34203974, 2021). "In addition to these, several as of yet not replicated studies on viral myocarditis, carcinogenesis, and obesity even further expand the spectrum of potential roles of TNNI3K." (PMID 34203974, 2021). "Furthermore, interactions between TNNI3K variants and other genetic loci, such as ITIH4, have been linked to childhood obesity risk, suggesting that TNNI3K may influence obesity through complex genetic networks." (PMID 41082226, 2025). "Transcripts for several candidate genes for obesity were absent in the whole brain or absent in specific regions of the brain (Cyp17a1, Gdf15, Gpr151, Lmx1b, Olig3, Sbk1, Sim1, Skor1, Tnni3k)." (PMID 39920851, 2025).
cardiac hypertrophy (7 papers, 2013 to 2025). "Studies in mice have shown that TNNI3K is associated with cardiac hypertrophy, regeneration, and recovery after ischemia/reperfusion injury." (PMID 39635265, 2024). "Knockout B6 mice and transgenic mice with overexpression of mutated kinase-dead TNNI3K demonstrated subtle cardiac hypertrophy compared to mice harboring wild-type Tnni3k transgene." (PMID 37628941, 2023). "Taken together, results of genotype-phenotype association analysis suggested that Tnni3k might be involved in the modulation of heart rate, heart rhythm, myocardial hypertrophy, and systolic function as well as repolarization of ventricular myocardium." (PMID 37628941, 2023). "Several studies have associated increased TNNI3K levels with cardiac hypertrophy." (PMID 34203974, 2021). "TNNI3K has been shown in several in vitro and transgenic animal studies to promote adaptive and maladaptive cardiac hypertrophy by increasing cardiomyocyte area and sarcomere organization." (PMID 40354360, 2025). "Nevertheless, a more detailed study would be of great interest to elucidate the relation of normal expression levels of Tnni3k with the development of cardiac hypertrophy." (PMID 34203974, 2021). "To investigate the role of TNNI3K in cardiac hypertrophy, we generated transgenic mouse lines with overexpression of human TNNI3K specifically in the heart." (PMID 23472207, 2013). "Up to date, little is known about the downstream targets of TNNI3K that are involved in the regulation cardiac hypertrophy." (PMID 23472207, 2013). "In a rat model of cardiac hypertrophy generated by transverse aortic constriction, myocardial TNNI3K expression was significantly increased by 1.62 folds (P<0.05) after constriction for 15 days." (PMID 23472207, 2013). "In 2015, a study showed that miR-223 directly targets TNNI3K and suppresses cardiac hypertrophy." (PMID 34203974, 2021). "However, the activities of Akt and ERK were not changed by TNNI3K overexpression either in vivo or in vitro, suggesting TNNI3K promotes cardiac hypertrophy through other signaling pathway." (PMID 23472207, 2013). "Notably, TNNI3K is also thought to be a promoter of physiological cardiac hypertrophy, so miR-223-3p may target TNNI3K to suppress either physiological or pathological cardiac hypertrophy." (PMID 33553260, 2020). "TNNI3K-KDtg mice presented signs of cardiac hypertrophy although it was not as high as in the TNNI3Ktg model." (PMID 34203974, 2021). "Therefore, we believe that the TNNI3K overexpression leads to an adaptive cardiac hypertrophy rather than maladaptive hypertrophy." (PMID 23472207, 2013).